LINC00609 (long independently transcribed non-coding RNA 609)
Synonyms: uc.373
Gene: Long non-coding RNA gene on chromosome 14 (35,897,884 to 36,235,609, forward strand). Ensembl gene ENSG00000257585.
Diseases named in the same sentence as LINC00609 in open-access papers:
LINC00609 is named in the same sentence as 2 diseases in open-access papers, as found by Europe PMC text mining. Sharing a sentence is not in itself a finding about the gene and the disease. The quoted sentences say what the papers report.
cancer (1 paper, 2021). A tumor composed of atypical neoplastic, often pleomorphic cells that invade other tissues. "More importantly, no study has reported the roles of LINC00609, AC012615.1, and USP32P3 in cancers." (PMID 34880375, 2021).
LINC00609 also shares sentences with these, for which no sentence is quoted: glioma (1 paper).